CHST11 (carbohydrate sulfotransferase 11)
Diseases named in the same sentence as CHST11 in open-access papers (continued):
Sharing a sentence is not in itself a finding about the gene and the disease.
pancreatic cancer (3 papers, 2022 to 2025). "Spearman correlation further indicated that CHST11 expression was positively associated with multiple NRGs, suggesting a potential mechanistic link between necroptosis and pancreatic cancer progression." (PMID 41346619, 2025). "Meanwhile, it identifies that this gene is linked to poor prognosis of pancreatic cancer, and this prognostic association is closely related to the role of CHST11 in T cells and malignant epithelial cells." (PMID 41346619, 2025). "In contrast, CTSC was a risk factor for pancreatic cancer via Mendelian randomization, with a significant positive correlation with CHST11 in TCGA (R = 0.44) and higher expression in naïve T cell_pos than in naïve T cell_neg." (PMID 41346619, 2025). "This study, through multi-omics data, reveals that CHST11 may be associated with necroptosis and is closely related to the malignant prognosis of pancreatic cancer." (PMID 41346619, 2025). "During this process, we also applied Mendelian randomization to screen for genes associated with pancreatic cancer from the differentially expressed genes and analyzed the prognostic characteristics of these genes and their association with CHST11 using transcriptome datasets." (PMID 41346619, 2025). "Mendelian randomization identified CTSC as an adverse factor for pancreatic cancer; TCGA data showed CTSC was significantly positively correlated with CHST11 and associated with poor prognosis." (PMID 41346619, 2025). "Results showed that CHST11 had high overall expression in pancreatic cancer tissues and shared significant co-expression regions with CTSC in spatial distribution." (PMID 41346619, 2025). "In pancreatic cancer tissues, CHST11 expression was predominantly observed in T cells, macrophages, and neutrophils, while in adjacent normal tissues, it was mainly expressed in T cells." (PMID 41346619, 2025). "In our study, we focused on pancreatic cancer malignant epithelial cells and found CHST11 was highly expressed in Ep_KRT6A and Ep_VGLL1 cells." (PMID 41346619, 2025). "Consistent with this, CHST11 was highly expressed in T cells, NK cells, MDSCs, and cDC1s in mouse pancreatic cancer tissues." (PMID 41346619, 2025). "Moreover, we revealed the prognostic role of CHST11 in pancreatic cancer through multi-omics analysis and explored its potential synergistic effects with immune regulation, cellular exhaustion, and CTSC." (PMID 41346619, 2025). "We found CHST11 correlated with poor prognosis in multiple pancreatic cancer prognostic datasets." (PMID 41346619, 2025). "We further explored CHST11’s association with non-immune cells in pancreatic cancer, finding it mainly localized to fibroblasts and epithelial cells." (PMID 41346619, 2025). "As CHST11 is a key enzyme for glycosaminoglycan sulfation, these results suggest CHST11+ naive T cells in pancreatic cancer may have "Th2 differentiation tendency" and promote T cell exhaustion by enhancing apoptosis sensitivity via the FAS/FASLG pathway." (PMID 41346619, 2025). "Few studies have explored CHST11’s prognostic role and mechanisms in pancreatic cancer." (PMID 41346619, 2025). "Additionally, PCR, combined TCGA-GTEx analysis, and immunohistochemistry confirmed higher CHST11 expression in pancreatic cancer tissues and cells." (PMID 41346619, 2025). "In parallel with our findings in the pathway enrichment analysis, in a pancreatic cancer related complementary EMT model, it was shown that CHST11, a modifier of glycosaminoglycan sulfation was significantly upregulated in the EMT model." (PMID 36465388, 2022). "For CHST11, low expression was observed in 3 normal pancreatic tissues, while differential expression was found in pancreatic cancer tissues: of 8 patients, 2 were negative, 3 had weak expression, and 3 had moderate expression." (PMID 41346619, 2025).
pancreatic cancer (continued). "Spatial transcriptomics analysis showed high CHST11 expression in Ep_KRT6A and significant co-localization between CHST11 and CTSC, suggesting they may synergistically promote pancreatic cancer progression." (PMID 41346619, 2025). "FHIT was identified as a protective factor for pancreatic cancer via Mendelian randomization, showing a significant negative correlation with CHST11 in TCGA (R = -0.23) and lower expression in naïve T cell_ CHST11pos than in naïve T cell_ CHST11neg." (PMID 41346619, 2025). "Meanwhile, CHST11 and CTSC may synergistically promote pancreatic cancer progression." (PMID 41346619, 2025).
breast invasive carcinoma (2 papers, 2011 to 2023). "The expression of CSPG4 and CHST11 in 15 primary invasive breast cancer clinical specimens was assessed by qRT-PCR." (PMID 21658254, 2011).
Clear cell renal cell carcinoma (2 papers, 2024 to 2025). "Clear cell renal cell carcinoma (ccRCC) is a common malignant tumor, and the role of carbohydrate sulfotransferase 11 (CHST11) in this cancer remains unclear." (PMID 38565604, 2024).
diffuse large B-cell lymphoma (2 papers, 2023 to 2025). "For example, KIAA1429 contributed to the development of diffuse large B-cell lymphoma by downregulating CHST11 expression via m6A modification." (PMID 40301310, 2025).
melanoma (2 papers, 2020 to 2025). A malignant, usually aggressive tumor composed of atypical, neoplastic melanocytes. "Overexpression of CHST3 and CHST11 have been linked to BC aggressiveness, relapse, and development of metastasis; in contrast, downregulation of CHST10 and CHST14 has been linked to invasive melanoma and to late stages of colon cancer progression, respectively." (PMID 32605588, 2020). "In normal melanocytes and B16F10 melanoma cells, similar effects of ARSB treatment on CHST15 and CHST11 expression were detected." (PMID 40562100, 2025). "Different transcription factors regulate the expression of CHST11 and CHST15 in the melanoma cells." (PMID 40562100, 2025).
metastatic disease (2 papers, 2018 to 2022). "Here, CHST11 expression was elevated in patients treated with ADT, in high-risk tumors, and in patients with metastatic disease." (PMID 35963852, 2022). "CHST11 levels dropped by more than 60% in non-metastatic (p < 0.05) and around 85% in metastatic tumors (p < 0.01), affecting 85 and 100% of samples respectively." (PMID 29940912, 2018).
Obesity (2 papers, 2019 to 2025). Accumulation of substantial excess body fat. "For example, CHST11 is a reported target of PPAR-gamma, involved in lipid accumulation in adipocytes, while KSR2 regulates energy intake and expenditure and has been implicated in obesity and IR." (PMID 40699860, 2025).
osteoarthritis (2 papers, 2013 to 2016). A noninflammatory degenerative joint disease occurring chiefly in older persons, characterized by degeneration of the articular cartilage, hypertrophy of bone at the margins and changes in the synovial membrane. "The gene encoding this sulfotransferase enzyme (C4ST-1/CHST11) has also been identified as a major osteoarthritis susceptibility gene in a recent large genome-wide association study (arcOGEN Consortium and arcOGEN Collaborators, 2012)." (PMID 23576310, 2013).
prostate carcinoma (2 papers, 2022 to 2024). A carcinoma that arises from epithelial cells of the prostate gland. "Combined, these data show that CSA constitutes the majority of CS in prostate cancer and is regulated by AR via CHST11." (PMID 35963852, 2022). "The result was corroborated in a second validation cohort of n > 196 mixed stage patients (IST cohort), supporting an inverse relationship between CHST11 expression and AR signaling in prostate cancer." (PMID 35963852, 2022). "For instance, we have reported that the enzyme CHST11, which is one of several enzymes essential for oncofetal CS synthesis, is regulated by the androgen receptor in prostate cancer, suggesting a direct link between androgen levels and oncofetal CS presentation." (PMID 39406935, 2024). "Combined, these data show that CHST11 is an AR-repressed gene in prostate cancer." (PMID 35963852, 2022). "We next investigated whether CHST11 indeed was responsible for CSA synthesis in prostate cancer." (PMID 35963852, 2022). "We next investigated whether the CHST11-ARE was functional in prostate cancer cells." (PMID 35963852, 2022). "However, pre-cell death assessment of CSA expression at 48 h after CHST11 knockdown, showed a significant reduction of CSA chains in PC-3 cells, supporting the idea that CHST11 is driving CSA expression in prostate cancer." (PMID 35963852, 2022).
respiratory failure (2 papers, 2014 to 2019). The significant impairment of gas exchange within the lungs resulting in hypoxia, hypercarbia, or both, to the extent that organ tissue perfusion is severely compromised. "Chst11-mutant mice died within 6 hours of birth due to respiratory failure, severe dwarfism and chondrodysplasia (i.e., abnormalities in the cartilage growth plate and chondrocyte columns)." (PMID 31905796, 2019).
autoimmune disorder (1 paper, 2023). "As SLE is an autoimmune disorder of the connective tissue, the other top GSEA term is ‘chondrocyte development’, represented by the genes CHST11, COL11A, EXT1, and TGFBR2." (PMID 37048133, 2023).
B-cell chronic lymphocytic leukemia (1 paper, 2023). "The expression of CHST11 in B-cell chronic lymphocytic leukemia was reported to be dysregulated." (PMID 37076815, 2023).
bipolar disorder (1 paper, 2015). A disorder of the brain that causes unusual shifts in mood, energy, activity levels and the ability to carry out day-to-day tasks. "This SNP is within intron-2 of CHST11, a gene which has previously been reported as bipolar disorder-associated." (PMID 25887412, 2015).
COVID-19 (1 paper, 2023). A disease caused by infection with severe acute respiratory syndrome coronavirus 2. "Recently, CHST11 and CHST15 overexpression in the vascular smooth muscle cells was linked to the severe lung pathology in COVID-19 patients." (PMID 37545696, 2023). "They found that increased CHST11 and CHST15 activity may lead to severe lung pathology in coronavirus disease 2019 (COVID-19) patients." (PMID 37545696, 2023). "Carbohydrate sulfotransferase 11 mRNA expression was increased by 3.1 times (N = 9, P < 0.001) and CHST15 expression was 2.1 times (N = 15, P < 0.001) higher in the vascular smooth muscle cells of COVID-19 patients that had severe lung manifestations." (PMID 37545696, 2023).
cutaneous lupus erythematosus (1 paper, 2023). An autoimmune disorder that manifests as different lupus-specific skin disorders; it can occur with systemic lupus erythematosus, or as a singular disease. "CHST11, which attaches sulfates to the 4-position of unsulfated chondroitin, the major component of cartilage, was found to be highly expressed in cutaneous lupus erythematosus." (PMID 37048133, 2023).
endometrial cancer (1 paper, 2024). Primary or metastatic malignant neoplasm involving the endometrium (mucous membrane that lines the endometrial cavity). "Relevant studies have indicated that CHST11 may promote the progression of endometrial cancer by activating pathways such as the Wnt signaling pathway and promoting epithelial-mesenchymal transition." (PMID 38565604, 2024).
fibrosis (1 paper, 2025). the formation of excess fibrous connective tissue in an organ or tissue in a reparative or reactive process. "Additionally, CHST11 promotes tumor malignancy and the production of fibrosis activators; TGF-β and INF-γ induce CHST11 expression in fibrosis models and regulate CHST11-related molecules, indicating CHST11-fibroblast associations in pulmonary fibrosis." (PMID 41346619, 2025).
intellectual impairment (1 paper, 2020). "Also, with important roles in immune regulation, the genetic variation and methylation of the CHST11 gene, for which we found a methylated CpG site associated with intellectual impairment, has been linked to neurodevelopmental disorders." (PMID 33308293, 2020).
invasive ductal carcinoma (1 paper, 2015). "To investigate the association of CHST11 overexpression with tumor progression, we interrogated another dataset in the Oncomine database, comparing the expression of CHST11 between ductal carcinoma in situ (DCIS) and invasive ductal carcinoma (IDC)." (PMID 25586191, 2015).
non-small cell lung carcinoma (1 paper, 2024). A group of at least three distinct histological types of lung cancer, including non-small cell squamous cell carcinoma, adenocarcinoma, and large cell carcinoma. "CHST11 may promote the metastasis of non-small cell lung cancer cells through dysregulation of ceruloplasmin and intracellular iron balance." (PMID 38565604, 2024).
ovarian tumours (1 paper, 2023). "The study has shown that CHST11, CHST12 and CHST15 messenger ribonucleic acid (mRNA) tissue expressions in the malignant ovarian tumours were increased compared to the expressions in the non-malignant ovarian tumours (N = 95, P < 0.05 for each gene expression)." (PMID 37545696, 2023).
prostate adenocarcinoma (1 paper, 2022). "AR directly represses transcription of the 4-O-sulfotransferase gene CHST11 under basal androgen conditions, maintaining steady-state CS in prostate adenocarcinomas." (PMID 35963852, 2022).
prostate tumor (1 paper, 2022). "This upregulation of CHST11 after AR inhibition or loss was confirmed in three independent human prostate tumor cohorts (VPC, IST, and UW cohorts) of 435 patients combined." (PMID 35963852, 2022). "Combined, these data show that elevated CHST11 expression inversely correlates with AR signaling activity in prostate tumors." (PMID 35963852, 2022). "We show that CHST11 is an AR-repressed gene and that CSA is an essential component of the prostate tumor glycocalyx that supports progression of AR-indifferent CRPC." (PMID 35963852, 2022).
T-cell lymphoma (1 paper, 2015). "To determine whether deletion of CHST11 and/or MIR3922 is likely to underlie the combined phenotype of skeletal malformation and T-cell lymphoma in this family, we attempted to obtain biological material from the proband’s affected (deceased) sister but were ultimately unsuccessful." (PMID 26436107, 2015).
triple-negative breast carcinoma (1 paper, 2017). An invasive breast carcinoma which is negative for expression of estrogen receptor (ER), progesterone receptor (PR), and human epidermal growth factor receptor 2 (HER2). "Findings to-date indicate a link between the expressions of carbohydrate sulfotransferase-11 (encoded by CHST11) which is involved in decorating CSPG4 with chondroitin sulfate and the metastatic behavior of triple-negative breast cancer cells." (PMID 29375561, 2017).
type 2 diabetes (1 paper, 2024). "The carbohydrate sulfotransferase 11 and histo-blood group ABO system transferase exhibited high-support genetic colocalization evidence and were found to affect PC carcinogenesis partially through modulating body mass index and type 2 diabetes, respectively." (PMID 38858729, 2024).
cancer (18 papers, 2013 to 2025). A tumor composed of atypical neoplastic, often pleomorphic cells that invade other tissues. "Dot plots and UMAP showed CHST11 was mainly expressed in cancer-associated fibroblasts and in Ep_KRT6A/Ep_VGLL1 cells among malignant epithelial cells." (PMID 41346619, 2025). "Recent studies have indicated that CHST11 is associated with the development of several types of cancer." (PMID 38565604, 2024). "According to previous studies, CHST11 is abnormally expressed in various malignant tumors, and it is closely associated with the clinicopathological features of cancer and the prognosis of cancer patients." (PMID 38565604, 2024). "Previous studies reported CHST11 overexpression in various cancers, typically correlating with poor prognosis." (PMID 41346619, 2025). "The aberrant expression of CHST11 facilitates the proliferation, migration, and invasion of tumor cells and promotes the emergence of biological behavior characteristics of cancer stem cells." (PMID 38565604, 2024). "These analyses identified several cancer-related genes, including Kif26a, Acer2, Serpine1, Nr1d2, Efnb2, and Chst11, to be affected by ECS exposure." (PMID 39273313, 2024). "Here, we confirm that the CHST11 gene is overexpressed in cancer tissues compared to normal breast tissues and its expression correlates with more aggressive basal-like and HER2-amplified phenotypes in cell lines." (PMID 25586191, 2015). "CHST11 mRNA expression in human cancers was first analyzed using the TCGA RNA‐sequencing data." (PMID 36062845, 2023). "According to the KEGG analysis, CHST11 may participate in PD‐L1 expression and PD‐1 checkpoint pathway in cancer by regulating genes TICAM2, LAT, TLR2, CD4, STAT3, NFKBIE and CD3D." (PMID 36062845, 2023). "The data relate CHST11 expression to basal-like cancer cells." (PMID 25586191, 2015). "However, the clinical significance of CHST11 expression is yet to be established and more studies are needed to evaluate the expression of this gene in relation to cancer progression." (PMID 25586191, 2015). "Finally, we found major differences among the cancer cell lines in their expression of genes involved in glycosylation, including CHST11, CHST13, Ext1, HAS2 and HAS3, which may have an impact on the architectural organization of the spheroids." (PMID 39011470, 2024). "These evidences showed that CHST11 may exert a cancer‐promoting role in HCC." (PMID 36062845, 2023). "Therefore, in a WT condition where the levels of Gal-3 are gradually decreasing in tumor cells, the upregulation of CHST11 might contribute to the overall metastatic behavior of cancer cells." (PMID 31949431, 2019). "Carbohydrate sulfotransferases, such as CHST7, CHST11-13, or CHST15, have been suggested to be relevant in developing and progressing multiple types of cancer, as in PDA." (PMID 39098880, 2024). "It has been shown that CHST3, CHST7, CHST11-13 and CHST15 have functional relevance and prognostic potential in various cancer types." (PMID 37545696, 2023). "The study results revealed that there was significantly higher mRNA expression of CHST11, CHST12, CHST15 and CHST13 compared to non-malignant tumours." (PMID 37545696, 2023). "Thus, the underexpression of the CHST11 gene (coding C-4-ST) is implicated but not proven by the results, and other factors altering the sulfatase activity may play a role during cancer progression." (PMID 36230789, 2022). "Our results showed that the heat diffusion algorithm predicted 5 putative cancer gene CDH10, CHST11, GRM3, VAV1 and CCR4 from Tier 2 of the Cancer Gene Census6." (PMID 31500564, 2019). "CHST11 was also highly expressed in cancer tissues compared to normal tissues and the expression levels were significantly associated with tumor progression." (PMID 25586191, 2015).